SPRED1 (sprouty related EVH1 domain containing 1)
Description:
Tyrosine kinase substrate that inhibits growth-factor-mediated activation of MAP kinase (By similarity). Negatively regulates hematopoiesis of bone marrow (By similarity). Inhibits fibroblast growth factor (FGF)-induced retinal lens fiber differentiation, probably by inhibiting FGF-mediated phosphorylation of ERK1/2 (By similarity). Attenuates actin stress fiber formation via inhibition of TESK1-mediated phosphorylation of cofilin. Inhibits TGFB-induced epithelial-to-mesenchymal transition in lens epithelial cells (By similarity).
Synonyms: Spred-1; hSpred1; FLJ33903; PPP1R147; LGSS; NFLS
Tractability: Small molecule: a structure with a bound ligand is known. Antibody: UniProt places it where antibodies can reach, with high confidence; its Gene Ontology location is reachable by antibodies, with high confidence. PROTAC: UniProt records ubiquitination sites on it; ubiquitination databases record sites on it.
Gene: Protein-coding gene on chromosome 15 (38,252,139 to 38,357,249, forward strand). Ensembl gene ENSG00000166068.
Subcellular location: Cell membrane; Membrane, caveola; Nucleus
Subcellular location (Human Protein Atlas): Nucleoplasm
Pathways (Reactome):
Signal Transduction: FGFRL1 modulation of FGFR1 signaling; Regulation of RAS by GAPs
Disease: RAS signaling downstream of NF1 loss-of-function variants
Gene Ontology:
Molecular function: phosphatase binding; protein binding; protein kinase binding; protein serine/threonine kinase inhibitor activity; stem cell factor receptor binding
Biological process: negative regulation of angiogenesis; negative regulation of intracellular signal transduction; negative regulation of MAPK cascade; vasculogenesis involved in coronary vascular morphogenesis; negative regulation of epithelial to mesenchymal transition; negative regulation of ERK1 and ERK2 cascade; negative regulation of lens fiber cell differentiation; negative regulation of transforming growth factor beta receptor signaling pathway; regulation of MAPK cascade; negative regulation of cell migration involved in sprouting angiogenesis; regulation of signal transduction
Cellular component: cytoplasmic vesicle; cytosol; nucleoplasm; nucleus; plasma membrane; caveola; cytoplasm; membrane
Genetic constraint (gnomAD): Loss-of-function variants: 16 observed, 48.95 expected, observed/expected ratio (o/e) 0.33, 90% interval 0.22 to 0.5. The upper end of that interval is the gene's LOEUF score, 0.5, which puts it in group 2 of 6, group 1 being the genes least tolerant of losing a copy. Missense variants: 469 observed, 561.17 expected, observed/expected ratio (o/e) 0.84, 90% interval 0.77 to 0.9. Synonymous variants: 151 observed, 183.08 expected, observed/expected ratio (o/e) 0.82, 90% interval 0.72 to 0.94.
Gene-disease validity (ClinGen):
ClinGen rates the evidence that SPRED1 causes each of these diseases.
Legius syndrome (autosomal dominant): Definitive. Legius syndrome, also known as NF1-like syndrome, is a rare, genetic skin pigmentation disorder characterized by multiple cafC)-au-lait macules with or without axillary or inguinal freckling.
Homologues: Orthologues: chimpanzee SPRED1 (100% identical), macaque SPRED1 (99% identical), rabbit SPRED1 (95% identical), dog SPRED1 (95% identical), pig SPRED1 (94% identical), mouse Spred1 (93% identical), rat Spred1 (92% identical), guinea pig SPRED1 (91% identical), tropical clawed frog spred1 (56% identical), zebrafish spred1 (55% identical), Drosophila melanogaster Spred (30% identical), Caenorhabditis elegans unc-34 (19% identical), and 1 more. Paralogues in human: SPRED2 (52% identical), SPRED3 (34% identical), ENAH (18% identical), VASP (16% identical), EVL (16% identical).
Diseases named in the same sentence as SPRED1 in open-access papers:
SPRED1 is named in the same sentence as 79 diseases in open-access papers, as found by Europe PMC text mining. Sharing a sentence is not in itself a finding about the gene and the disease. The quoted sentences say what the papers report.
Legius syndrome (46 papers, 2011 to 2025). "Pathogenic variants in SPRED1 (Legius syndrome) were more frequent in UKBB (1:19,567 [95%CI: 1:13,150–1:29,116]) compared to MyCode (1:41,762 [95%CI: 1:15,185–1:130,367])." (PMID 39802765, 2024). "The difference in P/LP variant frequency in SPRED1 (Legius syndrome) in the UKBB (1:19,567) and MyCode cohorts (1:41,762) 24 is not explained by read depth differences in SPRED1 in the two cohorts (MyCode: 31.2; UK Biobank: 17.7)." (PMID 39802765, 2024). "The identified truncating variant SPRED1 p.R325Ter (Case 9) is linked to Legius syndrome, a rare RASopathy caused by inactivating mutations." (PMID 38654924, 2024). "In this study, we identified several severe loss-of-function mutations within the SPR domain of SPRED1 in individuals with Legius syndrome." (PMID 39510187, 2024). "Approximately 1–4% of patients with multiple CALM who meet the 1988 clinical diagnostic criteria for NF1 have Legius syndrome since they harbour SPRED1 pathogenic variants." (PMID 34928431, 2022). "Legius syndrome has been estimated to occur with a prevalence of 1:46,000–1:75,000 and is caused by pathogenic variants in the SPRED1 gene located on chromosome 15q13.2." (PMID 34928431, 2022). "A Spred1-/- mouse model for Legius syndrome exhibits a phenotype which models social phenotypes linked to ASD, with enhanced social dominance and deficits in USV communication, as well as impaired nesting behavior." (PMID 34311771, 2021). "SPRED1’s loss of heterozygosity is thought to play a role in pediatric acute myeloblastic leukemia; furthermore, there is some evidence that Legius syndrome is possibly associated with an increased risk for kidney tumors and lung cancers." (PMID 34325699, 2021). "Legius syndrome is a rare autosomal dominant disorder caused by heterozygous mutations in SPRED1, which negatively regulates activation of BRAF and CRAF and recruits NF1." (PMID 34828352, 2021). "Neurofibromatosis type 1 has an overlap clinical phenotype with Legius syndrome (MIM# 611431), originally termed “neurofibromatosis type 1-like syndrome” and caused by SPRED1 mutations." (PMID 35096710, 2021). "Nonetheless, the definitive association between pathogenic SPRED1 variations and tumor predisposition is complicated by the fact that Legius syndrome is very rare, therefore the amount of available evidence is currently insufficient." (PMID 34325699, 2021). "Given the normality of the NF1 gene, we analyzed the SPRED1 gene associated with the Legius syndrome, in order to prove a possible differential diagnosis." (PMID 33663580, 2021). "The neurofibromin-SPRED1 interaction interface provides a rationale for mutations observed in Legius syndrome." (PMID 32697994, 2020). "We mutated several of these residues in SPRED1 that cause Legius syndrome in order to test the relationship between the disease phenotype and NF1 binding by measuring the KD using ITC." (PMID 32697994, 2020). "The Legius syndrome patient mutations SPRED1(W31C) and (T102R) are unable to inhibit cell proliferation, presumably because they fail to bind NF1." (PMID 32697994, 2020). "Although many of the Legius-syndrome-associated mutations found in the SPRED1 gene result in premature stop codons, those that result in non-truncating missense mutations are often located within the EVH1 domain." (PMID 32697994, 2020). "The recently identified Legius syndrome, caused by germline mutations in the SPRED1 gene, shares milder symptoms with neurofibromatosis type 1, including CALM, axillary freckling, and sometimes macrocephaly." (PMID 32697994, 2020). "Loss of function mutations in SPRED1 cause Legius syndrome and an inability of SPRED1 to downregulate the Ras-MAPK pathway." (PMID 31466283, 2019).
Legius syndrome (continued). "SPRED1, recognized as the causative gene for Legius syndrome (OMIM #611431), interacts with SPRY2 that has been described as a causative OFC gene." (PMID 26561393, 2016). "Mutations in SPRED1 cause Legius Syndrome, a condition characterized by intertriginous freckling, lipomas, macrocephaly, learning disabilities and developmental delay." (PMID 27081556, 2015). "Mutations in SPRED1 have been reported to cause Legius Syndrome, a rare developmental disorder that shares some clinical features with Neurofibromatosis-1." (PMID 27081556, 2015). "Several SPRED1 variants, including sequence-based changes and large deletions/duplications, have been linked to Legius Syndrome." (PMID 27081556, 2015). "SPRED1 is a very efficient regulator of RAS and certain inherited SPRED1 mutants cause the Legius syndrome which belongs to the so-called “rasopathies” – diseases characterized by enhanced RAS signaling." (PMID 24970815, 2014). "Legius syndrome (MIM# 611431) was recently identified as a Neurofibromatosis type 1 (NF1)- like syndrome caused by heterozygous germline loss-of-function SPRED1 (MIM# 609291) mutations." (PMID 21089071, 2011). "Legius syndrome (LS) is an autosomal dominant disorder caused by germline loss-of-function mutations in the sprouty-related, EVH1 domain containing 1 (SPRED1) gene." (PMID 22384355, 2011). "Monoallelic pathogenic variants in the SPRED1 gene are known to cause Legius syndrome." (PMID 40437629, 2025). "This study demonstrated that the SPR domain of SPRED1 undergoes S-acylation, presumably S- palmitoylation and that several missense mutations in Legius syndrome impair the membrane localization of SPRED1 due to defective palmitoylation, leading to reduced Ras inactivation." (PMID 39510187, 2024). "To date, more than 100 missense mutations in SPRED1 have been identified in Legius syndrome." (PMID 39510187, 2024). "Furthermore, as the authors of the revised criteria admit, patients with the much rarer Legius syndrome, caused by a pathogenic variant in the SPRED1 gene, meet these criteria for NF1 as well." (PMID 38581124, 2024). "The revised diagnostic criteria for NF1, together with the newly formulated diagnostic criteria for Legius syndrome which include genetic testing for pathogenic variants in SPRED1, promise to facilitate the differential diagnosis of both disorders at an early age." (PMID 34928431, 2022). "Here, we examined ASD-linked behaviors in a Spred1-/- mouse model for Legius syndrome." (PMID 34311771, 2021). "Finally, Legius syndrome is caused by heterozygous mutations in SPRED1, whereas we have used a homozygous Spred1 mouse model in order to be able to robustly detect phenotypes." (PMID 34311771, 2021). "Legius syndrome is a rare RASopathy caused by loss-of-function mutations in the SPRED1 gene." (PMID 34311771, 2021). "Milder phenotypes associated with Legius syndrome relative to neurofibromatosis type 1 may be due to partial redundancy between SPRED1 and SPRED2 proteins." (PMID 32697994, 2020). "However, the structural details of the SPRED1-NF1 complex and the effects of the pathogenic mutations observed in Legius syndrome on SPRED1’s interaction with NF1 remain to be clarified." (PMID 32697994, 2020). "Legius syndrome is an autosomal dominant disorder caused by the loss-of-function SPRED1 mutations." (PMID 32014052, 2020). "Legius syndrome is caused by loss-of-function mutations in the SPRED1 gene (MIM*609291)." (PMID 31443423, 2019). "Similarly, loss of function of SPRED1 causes Legius syndrome, which can be confused clinically with neurofibromatosis type 1 (both genes act upstream of RAS signaling)." (PMID 30573688, 2018). "Neurofibromin and Sprouty-related EVH1 domain-containing protein 1 (Spred1) both act as negative regulators of the mitogen-activated protein kinase pathway and are associated with the rare diseases Neurofibromatosis type 1 and Legius syndrome, respectively." (PMID 28831766, 2017).
Legius syndrome (continued). "This case provides further evidence that post‐axial polydactyly identified on fetal imaging can be indicative of a SPRED1 variant, whilst also suggesting that cardiac abnormalities may need to be looked for with SPRED1 variants, representing a new feature of Legius syndrome." (PMID 40437629, 2025). "Case 35 with digenic findings SPRED1 p.Arg325Ter and TP63 p.Pro428Leu presented characteristic features of Legius syndrome (linked to SPRED1)." (PMID 40060932, 2025). "We generated mutant SPRED1 cDNAs with three missense mutations present in the KBD and 18 mutations in the SPR domain discovered in patients with Legius syndrome and evaluated its Ras repression activity by ERK reporter assay." (PMID 39510187, 2024). "Four primer sets of very long-range PCR (around 20-kb single amplicons) for the SPRED1 gene was set up to differential the diagnosis of Legius syndrome, and NGS sequencing was performed, very LAS (vLAS)." (PMID 34449562, 2021). "Spred1 knockout mice, a model for Legius syndrome, also have impaired hippocampal LTP, together with sustained LTD." (PMID 34828352, 2021). "The biochemical and clinical overlap between NF1 and Legius syndrome suggests that Spred1 mouse models can offer insights into the shared molecular mechanisms underlying both of these syndromes." (PMID 34311771, 2021). "In the case of eight genetically NF1 negative patients with CALMs (P29–33 and P38–40) additional Sprouty Related EVH1 Domain Containing 1 gene (SPRED1) analysis excluded the presence of Legius syndrome as well." (PMID 34325699, 2021). "Neurofibromatosis type 1 (NF1) is caused by mutations in the NF1 gene, whereas Legius syndrome, also known as NF1-like syndrome, is caused by mutations in the SPRED1 gene." (PMID 34229750, 2021). "Recently the co-occurrence of pathogenic variants in the NF1 and SPRED1 genes was observed using NGS in one family with NF1 and Legius Syndrome." (PMID 32575496, 2020). "We have previously demonstrated that SPRED1 overexpression decreased RAS-GTP following EGF stimulation in HEK293T cells and that SPRED1 mutants found in Legius syndrome were unable to decrease RAS-GTP." (PMID 32697994, 2020). "Previously, one more case of co-occurrence of NF1 and Legius Syndrome in the same family (with confirmed pathogenic variants in the NF1 and SPRED1 genes) was reported." (PMID 32575496, 2020). "Here, we report the co-occurrence of pathogenic variants in the NF1 and SPRED1 genes in six families with NF1 and Legius syndrome, using next-generation sequencing." (PMID 31443423, 2019). "Only one case of co-occurrence of NF1 and Legius syndrome in the same family (with confirmed pathogenic variants in the NF1 and SPRED1 genes) has previously been reported." (PMID 31443423, 2019). "Although loss-of-function frameshift mutation of SPRED1 was first reported in a child AML with Legius syndrome, neither mutation nor deletion of SPRED1 was common in AML." (PMID 35359401, 2022). "Legius syndrome is a rare RASopathy resulting from mutations in SPRED1 (Sprouty Related EVH1 Domain Containing 1), a member of the Spred protein family and negative regulator of Ras." (PMID 34311771, 2021). "Here, we investigated if a Spred1-/- mouse model for Legius syndrome recapitulates ASD-like symptoms, and whether targeting the Ras-MAPK pathway has therapeutic potential in this RASopathy mouse model." (PMID 34311771, 2021). "(Thr102Argfs*19) in SPRED1 gene, which allowed to diagnose Legius syndrome." (PMID 33663580, 2021). "Although Legius syndrome patients carry heterozygous loss-of-function mutations in SPRED1, we did not observe social dominance alterations in Spred1+/− mice." (PMID 34311771, 2021). "Our study also provides a structural explanation for the pathogenic mutations in SPRED1 and NF1 responsible for Legius syndrome and neurofibromatosis type 1, and it explains why SPRED1 interacts with NF1 GAP but not RASA1 GAP." (PMID 32697994, 2020).
Legius syndrome (continued). "Analysis of the neurofibromin-SPRED1 interface provides a rationale for mutations observed in Legius syndrome and suggests why SPRED1 can bind to neurofibromin but no other RasGAPs." (PMID 32697994, 2020). "SPRED1 is a negative regulator of the RAS–MAPK signaling pathway downstream of receptor tyrosine kinase signaling, and germline loss-of-function mutations in SPRED1 cause neurofibromatosis 1-like syndrome in humans." (PMID 26038114, 2015). "Legius syndrome (LS; MIM #611431) is an inherited disease caused by autosomal dominant loss-of-function (LOF) mutations in the sprouty-related, EVH1 domain containing 1 (SPRED1) gene (MIM #609291)." (PMID 22384355, 2011). "Of particular relevance to cerebrovascular pathology, mutations in SPRED1 have been reported to cause Legius syndrome with MMS and the role of SPRED1 in inhibiting ECs proliferation suggests that this may be responsible for the progressive cerebrovascular stenosis observed in this condition." (PMID 40508049, 2025). "Ultimately for the syndrome associated with SPRED1, experts agreed that nomenclature based on nosology or pathogenesis did not improve understanding of the condition and suggested retaining the name Legius syndrome since the term is established and not misleading." (PMID 34012067, 2021). "In addition to the clinical overlap between NF1 and Legius syndrome, at the biochemical level the SPRED1 protein interacts with neurofibromin, recruiting neurofibromin to the membrane and enabling Ras-GAP activity of neurofibromin and suppression of downstream ERK activation." (PMID 34311771, 2021). "Both tumor types had not been reported before in association with Legius syndrome and it is unclear whether there is a causal relationship between these tumors and the germline SPRED1 mutation." (PMID 21089071, 2011). "Because of the overlapping phenotype of Legius Syndrome with NF1, the SPRED1 gene was included in our panel." (PMID 32575496, 2020). "Furthermore, the phenotypic overlap with NF1 and Legius syndrome has led to the acknowledgment of CMMRD as a legitimate, but presumably rare, differential diagnosis in children without malignancy who are suspected of these syndromes but lack the causative NF1 or SPRED1 variants." (PMID 30740824, 2019). "If Legius syndrome is suspected (≥ 6 bilateral CALMs with or without skinfold freckling without further manifestations suggestive of NF 1), sprouty related EVH1 domain containing 1 (SPRED1) sequencing to confirm or exclude Legius syndrome is recommended." (PMID 39264447, 2025). "For the differential diagnosis of Legius syndrome, SPRED1 vLAS was added for the patients with no identified NF1 mutations (NF_09, 13, 14, 15, and 18) and for the patients with missense variants of undetermined pathological significance (NF_10, 11, and 12)." (PMID 34449562, 2021). "Social behavioral abnormalities in Spred1-/- mice are reversible upon acute pharmacological MEK inhibition, indicating a critical role for Ras-MAPK signaling in the regulation of social behavior and a novel therapeutic approach for Legius syndrome." (PMID 34311771, 2021). "SPRED1 Legius syndrome patient mutants W31C and T102R that fail to bind NF1 did not affect proliferation." (PMID 32697994, 2020). "However, these dermatological manifestations are not exclusive to NF1; for instance, Legius syndrome (MIM: 611431) also prominently features CALMs, although with distinct molecular pathogenesis involving pathogenic variants in the SPRED1 gene (MIM: 609291)." (PMID 39001468, 2024). "As a rare differential diagnosis, CMMRD testing may also be indicated in children without cancer who are suspected to have sporadic NF1 or Legius syndrome but in whom no germline NF1 or SPRED1 PV has been identified by comprehensive testing." (PMID 39420201, 2024).
Legius syndrome (continued). "Notably, Legius syndrome and NF1 have phenotypic overlap (including CALMs and freckling); however, no pathogenic SPRED1 mutations have been reported in individuals with Lisch nodules, neurofibromas, or optic pathway gliomas (OPGs)." (PMID 31466283, 2019).